TSG101 (tumor susceptibility 101)
Diseases named in the same sentence as TSG101 in open-access papers (continued):
Sharing a sentence is not in itself a finding about the gene and the disease.
cervical carcinoma (3 papers, 1999 to 2015). A carcinoma arising from either the exocervical squamous epithelium or the endocervical glandular epithelium. "Our previous study demonstrated a decreased expression of tumor susceptibility gene 101 (TSG101) in cervical cancer cells." (PMID 24765146, 2014). "The TSG101 gene was mapped to chromosome 11.p15.1–p15.2., a region that is associated with the loss of heterozygosity in several tumor types, including breast cancer and cervical cancer." (PMID 24765146, 2014). "In the present study, we confirmed TSG101 protein downregulation during cervical cancer development using immunohistochemical analysis." (PMID 24765146, 2014). "To identify the mechanism responsible for TSG101 downregulation during cervical cancer development, we analyzed the TSG101 promoter using cis-element cluster finder (Cister) software." (PMID 24765146, 2014). "To identify the mechanism responsible for TSG101 downregulation during cervical cancer development, we analyzed the TSG101 promoter using cis-element cluster finder software." (PMID 24765146, 2014). "High expression of LSF in cervical cancer HPV-positive cells suggests that this protein may be important in the regulation of TSG101 expression, as well as in cervical carcinogenesis." (PMID 24765146, 2014). "Our previous results demonstrated a decreased expression of TSG101 in cervical cancer cells." (PMID 24765146, 2014). "High expression of LSF in cervical cancer HPV-positive cells suggests that this protein may be involved in downregulation of the TSG101 gene promoter and HPV-dependent cervical carcinogenesis." (PMID 24765146, 2014). "The aim of the present study was to analyze TSG101 and LSF protein expression during cervical cancer development." (PMID 24765146, 2014). "The aim of this study was to analyze the TSG101 protein and LSF expression levels during cervical cancer development." (PMID 24765146, 2014). "To explore whether TSG101 depletion has the same effects in other cell lines as in HT1080 cells, we examined the effect of TSG101 depletion on MMP-9 mRNA expression in U2OS osteosarcoma and HeLaS3 cervical carcinoma cells." (PMID 26608825, 2015). "Quantitive immunohistochemical analysis based on the percentage of TSG101-immunopositive cells revealed a significantly (P<0.05) lower percentage of TSG101-immunopositive cells in cervical cancer and HSIL samples compared with that in non-tumor (HPV-negative) cells." (PMID 24765146, 2014).
nasopharyngeal carcinoma (3 papers, 2016 to 2023). A carcinoma arising from the nasopharyngeal epithelium. "Here, we confirmed that the presence of TSG101∆154-1054 mRNA indeed caused an accumulation of the TSG101 protein in biopsies of human nasopharyngeal carcinoma (NPC), which was recapitulated by the overexpression of TSG101∆154-1054 in the NPC cell line TW01." (PMID 30759747, 2019). "We demonstrated previously that TSG101 contributes to Rta-mediated late gene activation in the productive lytic cycle of Epstein Barr virus, a DNA virus that is implicated in nasopharyngeal carcinoma (NPC)." (PMID 30759747, 2019). "We have also demonstrated that TSG101 cooperated with a viral lytic transactivator Rta to promote late genes activation of Epstein-Barr Virus (EBV), a DNA virus related with the development of nasopharyngeal carcinoma (NPC)." (PMID 26811492, 2016).
neuroblastoma (3 papers, 2014 to 2019). Neuroblastoma (NB) is the most common solid, extracranial childhood tumor. "With another approach, double transfection of LRSAM1 siRNA in neuroblastoma SH-SY5Y cells caused a >70% decrease of LRSAM1 levels which also resulted to an approximately 50% reduction of TSG101 levels." (PMID 30726272, 2019). "Consistent with Western blotting and previous studies, TSG101 and Alix were identified in exosomes isolated from neuroblastoma cells." (PMID 25944692, 2015).
osteosarcoma (3 papers, 2013 to 2020). A usually aggressive malignant bone-forming mesenchymal neoplasm, predominantly affecting adolescents and young adults. "TSG101 deficiency in Saos-2 human osteosarcoma cells was accompanied by an increased abundance of p21 mRNA and protein and the retardation of cell proliferation." (PMID 24244542, 2013).
adenocarcinoma of the gallbladder (2 papers, 2014 to 2015). "Moreover, it has been recently reported that positive TSG101 expression is significantly associated with invasion of adenocarcinoma of the gallbladder." (PMID 26608825, 2015).
adenosquamous carcinoma (2 papers, 2014 to 2025). A carcinoma composed of malignant glandular cells and malignant squamous cells. "The overexpression of TSG101 causes adenosquamous carcinomas that originate from luminal epithelial cells of the main mammary ducts after a median latency of 10 months." (PMID 40624726, 2025). "Females overexpressing TSG101 develop ductal hyperplasia, adenomyoepitheliomas, and palpable adenosquamous carcinomas at an average latency of approximately ten months." (PMID 40624726, 2025). "It is therefore possible that the activation of Wnt signaling in TSG101-induced adenosquamous carcinomas promotes cellular features independently of other oncogenic functions of TSG101." (PMID 40624726, 2025). "The atypical expression pattern of the MMTV-tTA-driven H2B-GFP reporter in basal epithelial cells within early TSG101-overexpressing preneoplastic lesions is retained in adenosquamous carcinomas." (PMID 40624726, 2025). "Despite the broad activation of JAK/STAT signaling cascades and low-grade histopathological features of these adenosquamous carcinomas, the TSG101-induced tumors lacked active STAT1, which is a suggested tumor suppressor." (PMID 40624726, 2025).
colon cancer (2 papers, 2021 to 2024). "It has been shown that the gene silencing of tumor susceptibility gene 101 (TSG101), a member of Vps protein family which involves in exosome trafficking, inhibits exosome production in colon cancer cells." (PMID 34078376, 2021). "Similarly as we reported for RKO colon cancer cells, depletion of TSG101 or VPS28 in HEK293 cells led to a strong intracellular accumulation of ubiquitin, likely due to the impairment of multiple ESCRT-I-mediated degradation processes." (PMID 39560723, 2024).
endometrial cancer (2 papers, 1999 to 2024). Primary or metastatic malignant neoplasm involving the endometrium (mucous membrane that lines the endometrial cavity). "Furthermore, an attempt to investigate the usefulness of the loss of TSG101 expression as a possible diagnostic marker for endometrial cancer showed 68% sensitivity and 68% specificity (AUC = 0.75; p = 0.0002), with a cut-off of 25% of cells expressing this marker." (PMID 38607019, 2024). "Our results suggest that high level of expression of TSG-101 is rare in endometrial cancer, and in most cases of EC its expression is low." (PMID 38607019, 2024). "Our study showed that a significantly lower percentage of endometrial cancers had high TSG101 expression compared to the normal control tissue (4% vs 36%; p = 0.0312)." (PMID 38607019, 2024). "Endometrial cancer was diagnosed in those with a lower level of TSG101 expression than in those with a cancer-free endometrium." (PMID 38607019, 2024). "Increased TSG101 expression was found in papillary thyroid cancers and tumors of the breast, ovary, and gastrointestinal tract, while its reduced expression was observed in cervical and endometrial cancers." (PMID 38607019, 2024). "Decreased expression of TSG101 may be a marker of endometrial cancer, and increased expression of LSF when diagnosed with endometrial cancer may indicate greater advancement of the disease." (PMID 38607019, 2024). "A much lower level of TSG101 expression was observed in endometrial cancer than in the non-cancerous endometrium, and it may have utility as a diagnostic marker of endometrial cancer." (PMID 38607019, 2024). "Although literature reports on the relationship between TSG101 and LSF are scarce, and the correlations we found are weak, linking these two markers could be useful in the diagnosis and assessment of prognosis of endometrial cancer, but this issue requires further research." (PMID 38607019, 2024).
lymphoma (2 papers, 2021 to 2022). A malignant (clonal) proliferation of B- lymphocytes or T- lymphocytes which involves the lymph nodes, bone marrow and/or extranodal sites. "The EVs markers; Tsg101 and CD63, and the lymphoma markers; CD45, CD79a, CD21, were detected in all EV samples." (PMID 36125986, 2022). "Our data showed these lymphoma vesicles did not strongly express CD63, LAMP-1, CD9, or TSG101." (PMID 33513976, 2021).
multiple myeloma (2 papers, 2022 to 2023). "BG45, an HDAC3-selective inhibitor, downregulates TSG101 and reduces the secretion of exosomes loaded with tumor-promoting miRNAs in multiple myeloma." (PMID 36320056, 2022). "Recently, it was reported that system Xc− mediated glutamate export enhanced exosome secretion in multiple myeloma and bone marrow stromal cells by upregulating the expression of Rab27a, TSG101, Alix, and VAMP7, thereby contributing to bortezomib resistance in multiple myeloma." (PMID 36320056, 2022).
oral cancer (2 papers, 2020 to 2022). "More recently, label-free quantification was used to identify 415 proteins in CD63+/CD9+/TSG101+ EVs from the plasma of patients with oral cancer." (PMID 33158181, 2020). "Building on this, another study revealed that some miRNAs were exclusive (miR-302b-3p and miR-517b-3p) to CD63+/CD9+/Alix+/TSG101+ EVs from the saliva of patients with oral cancer compared with controls whereas others were up-regulated (miR-512-3p and miR-412-3p)." (PMID 33158181, 2020).
spongiform encephalopathy (2 papers, 2015 to 2022). "Moreover, TSG101-null-mutant mice developed the same severe spongiform encephalopathy as MGRN1-mutant mice." (PMID 36012221, 2022).
thyroid cancer (2 papers, 2019 to 2020). "Recent TSG101 knockdown experiments implicated the function of TSG101 protein in anoikis (cell-detachment-induced apoptosis) resistance of thyroid cancer, which is a prerequisite for metastasis." (PMID 30759747, 2019).
acute pancreatitis (1 paper, 2020). An acute inflammatory process that leads to necrosis of the pancreatic parenchyma. "Analysis by immunoblotting confirmed the presence of exosome marker TSG101 and the absence of calnexin in both exosomes from BICR-18 and from acute pancreatitis plasma origin." (PMID 33353210, 2020).
adenovirus infection (1 paper, 2012). "Infection of NIH3T3 cells (wildtype for Tsg101) with AdCre did not lead to an elevation of activated MAP kinases (lanes 1 and 2), suggesting that the increase in pErk1/2 levels in AdCre-infected Tsg101fl/fl MEFs was not due to adenovirus infection per se but rather due to the lack of Tsg101." (PMID 22479596, 2012).
anemia (1 paper, 2023). A reduction in the number of red blood cells, the amount of hemoglobin, and/or the volume of packed red blood cells. "The PT/SAP domain within the HIV-1 Gag p6 region interacts with the putative ubiquitin regulator tumor susceptibility gene 101 (TSG101), while the LYPXnL domain found in anemia virus Gag associates with ALG-2 interacting protein X (ALIX)." (PMID 37112965, 2023).
asthenozoospermia (1 paper, 2021). "The exosomes isolated from normozoospermic men and asthenozoospermia patients were further identified by the presence of equal amounts of universal exosomal markers (CD63 and TSG101) based on immunoblotting." (PMID 34326815, 2021).
Cachexia (1 paper, 2021). Severe weight loss, wasting of muscle, loss of appetite, and general debility related to a chronic disease. "Furthermore, we detected the exosomal markers Hsp70, TSG101, and CD9 in LLC-EVs and colon-26 (C26)-derived EVs (C26-EVs; C26 that also induce cachexia in mice) by western blotting analysis." (PMID 33510128, 2021).
cardiac ischemia (1 paper, 2020). "To further examine the role of Tsg101 on the subcellular distribution of Glut-4 during cardiac ischemia, we utilized an inducible cardiac-specific Tsg101 knockdown (Tsg101-KD) mouse model." (PMID 32839388, 2020).
COVID-19 (1 paper, 2022). A disease caused by infection with severe acute respiratory syndrome coronavirus 2. "Consistently, SARS-CoV-2 infection triggered secretion of ACE2+TSG101+ EVs by human pneumocyte A549 cells overexpressing ACE2, implying that upregulated production of ACE2+ EVs is part of the innate response to SARS-CoV-2 infection in COVID-19 patients." (PMID 35058437, 2022).
endometriosis (1 paper, 2023). The growth of functional endometrial tissue in anatomic sites outside the uterine body. "Fallopian tube epithelial cells from endometriosis patients and controls were used as control samples, and CD9 and TSG101 were almost undetectable in the control samples." (PMID 37409222, 2023).
fibrosarcoma (1 paper, 2021). A malignant mesenchymal fibroblastic neoplasm affecting the soft tissue and bone. "Results from dot blot and western blot analysis demonstrated that GM1 ganglioside, and TSG101, HSC70 and GAPDH proteins were contained in exosomes from the WEHI-164 fibrosarcoma cell line." (PMID 33497388, 2021).
Flavivirus Infections (1 paper, 2022). Infections with viruses of the genus FLAVIVIRUS, family FLAVIVIRIDAE. "As the expression of ISG15 enhances the effects of the ESCRT protein depletion during flavivirus infection and TSG101 can be targeted by ISG15 during IAV infection, we investigated the effects of ISG15 on the ESCRT proteins during flavivirus infection." (PMID 34851141, 2022). "In the context of MBFV, infection results in the recruitment of the ESCRT proteins TSG101, CHMP2, and CHMP4 to orchestrate virus assembly at the ER, but how ISGylation precisely influences ESCRT recruitment in flavivirus infection is not understood." (PMID 34851141, 2022).
gastric adenocarcinoma (1 paper, 2014). "Certain studies have found that TSG101 is overexpressed in the vincristine-resistant human gastric adenocarcinoma cell line, SGC7901/VCR." (PMID 24944680, 2014).
gastroesophageal reflux disease (1 paper, 2020). A chronic disorder characterized by reflux of the gastric and/or duodenal contents into the distal esophagus. "The active form of the prazole that binds covalently to Cys residues in the H+/K+-ATPase for gastroesophageal reflux disease (GERD) treatment or to C73 in Tsg101 for inhibition of HIV-13 is the sulfenamide derivative of the prodrug." (PMID 32132561, 2020).
glioma (1 paper, 2025). A benign or malignant brain and spinal cord tumor that arises from glial cells (astrocytes, oligodendrocytes, ependymal cells). "For example, TSG101 deficiency in glioma cells impairs actin cytoskeletal organization, resulting in diminished migratory and invasive potential." (PMID 40149859, 2025).
Hepatic fibrosis (1 paper, 2022). The presence of excessive fibrous connective tissue in the liver. "Here we demonstrate that in hepatic fibrosis, TGF-β stimulates the palmitoylation of hexokinase 1 (HK1) in hepatic stellate cells (HSCs), which facilitates the secretion of HK1 via large extracellular vesicles in a TSG101-dependent manner." (PMID 36192599, 2022).
hepatoblastoma (1 paper, 2024). Hepatoblastoma (HB) is a malignant hepatic tumor and is the most common pediatric liver cancer. "To investigate whether reduced expression of the chosen genes occurred also in other cell types, we performed qRT-PCR analysis in HepG2 hepatoblastoma cell line with siRNA-mediated removal of TSG101 or VPS28 proteins using siTSG101#2 and siVPS28#1 or CRISPR-Cas9-mediated knock-out of TSG101 gene." (PMID 39560723, 2024).
Hypertension (1 paper, 2025). The presence of chronic increased pressure in the systemic arterial system. "The significantly reduced CD9 expression with unchanged TSG101 levels in hypertensive exosomes raises interesting questions about EV surface markers and their role in hypertension." (PMID 41356094, 2025).
hypertrophy (1 paper, 2020). Hypertrophy is the increase in the volume of an organ or tissue due to the enlargement of its component cells. "For example, CD63 and TSG101 were decreased in TAC EVs and these markers were previously reported to be involved in cardiac fibrosis and hypertrophy, respectively." (PMID 32485073, 2020).
invasive breast carcinoma (1 paper, 2025). A carcinoma that infiltrates the breast parenchyma. "The notion that TSG101 executes primarily pro-tumorigenic roles in breast carcinogenesis was also supported by immunostaining results that showed that this protein is expressed at higher levels in invasive breast cancer cases." (PMID 40624726, 2025).
ischemia (1 paper, 2020). A hypoperfusion of the BLOOD through an organ or tissue caused by a PATHOLOGIC CONSTRICTION or obstruction of its BLOOD VESSELS, or an absence of BLOOD CIRCULATION. "To dissect how Tsg101 regulates Glut-4 transport to the plasma membrane during ischemic injury, we first determined the distribution of Glut-4 and Tsg101 in mouse heart sections, collected at ex vivo pre-ischemia and post-ischemia." (PMID 32839388, 2020). "Taken together, these data suggest that Tsg101 could interact with Glut-4 and may promote its accumulation at the plasma membrane of cardiomyocytes upon ischemia." (PMID 32839388, 2020). "Furthermore, we found that both PM/nuclei-depleted intracellular fraction and sarcolemma Tsg101 levels were significantly augmented in both WT and TG hearts upon ischemia, compared to pre-ischemia conditions." (PMID 32839388, 2020). "More interestingly, under ischemia condition, Tsg101 could be translocated to the membrane edge of myocytes (white arrows), and co-localized with sarcolemma Glut-4 (white arrows)." (PMID 32839388, 2020). "Hence, overexpression of Tsg101 in mouse hearts and cardiomyocytes may alleviate the deleterious effects during ischemia and hypoxia, thereby rendering protection from tissue damage and cardiomyocyte death after reperfusion." (PMID 32839388, 2020).
ischemic heart disease (1 paper, 2020). "Our findings define Tsg101 as a novel regulator of cardiac Glut-4 trafficking, which may provide a new therapeutic strategy for the treatment of ischemic heart disease." (PMID 32839388, 2020).
kidney injury (1 paper, 2024). Trauma to the kidney. "Protein markers of uEVs (for example, the tumor susceptibility 101 protein and the ALG-2-interacting protein X) were increased 7 days after ischemia–reperfusion injury in rats, which may point to the underlying mechanisms during the transition of acute kidney injury to renal fibrosis." (PMID 39334890, 2024).
lung adenocarcinoma (1 paper, 2024). A carcinoma that arises from the lung and is characterized by the presence of malignant glandular epithelial cells. "Lung adenocarcinoma-derived exosomal miR-19b-3p (size range of 100 nm, marker proteins CD9, CD81) and miR-10b (bilayer membrane structure, typical “cupped” structure, marker proteins TSG101,CD63,CD81) facilitate macrophage polarization to the M2 type to promote lung adenocarcinoma development." (PMID 39165926, 2024).
lung squamous cell carcinoma (1 paper, 2021). "The abundance of TSG101, which was detected in 13 LAC samples (0.8 ± 0.2 nM) and five SqC samples (3.8 ± 1.5 nM), was significantly higher for lung squamous cell carcinoma (p-value = 0.00539)." (PMID 34684727, 2021).